RRM2 (ribonucleotide reductase regulatory subunit M2)
Description:
Provides the precursors necessary for DNA synthesis. Catalyzes the biosynthesis of deoxyribonucleotides from the corresponding ribonucleotides. Inhibits Wnt signaling.
Synonyms: RR2; FLJ25102; C2orf48; R2; RR2M
Tractability: Small molecule: an approved drug acts on it; it belongs to a druggable protein family. PROTAC: UniProt records ubiquitination sites on it; ubiquitination databases record sites on it; a small molecule that binds it is known.
Target class: Enzyme; Oxidoreductase
Gene: Protein-coding gene on chromosome 2 (10,120,698 to 10,211,725, forward strand). Ensembl gene ENSG00000171848.
Subcellular location: Cytoplasm; Nucleus
Subcellular location (Human Protein Atlas): Cytosol; Nucleoplasm
Pathways (Reactome):
Cell Cycle: G1/S-Specific Transcription
Gene expression (Transcription): Transcriptional Regulation by E2F6
Metabolism: Interconversion of nucleotide di- and triphosphates
Gene Ontology:
Molecular function: protein binding; ribonucleoside-diphosphate reductase activity, thioredoxin disulfide as acceptor; ferric iron binding; identical protein binding; oxidoreductase activity; protein homodimerization activity; ribonucleoside-diphosphate reductase activity, glutaredoxin disulfide as acceptor
Biological process: 2'-deoxyribonucleotide biosynthetic process; DNA repair; positive regulation of G1/S transition of mitotic cell cycle; ribonucleoside diphosphate metabolic process; deoxyribonucleotide biosynthetic process; dTMP biosynthetic process; positive regulation of mitotic cell cycle phase transition; protein heterotetramerization
Cellular component: cytoplasm; cytosol; nucleoplasm; nucleus; ribonucleoside-diphosphate reductase complex
Genetic constraint (gnomAD): Loss-of-function variants: 6 observed, 40.51 expected, observed/expected ratio (o/e) 0.15, 90% interval 0.08 to 0.29. The upper end of that interval is the gene's LOEUF score, 0.29, which puts it in group 1 of 6, group 1 being the genes least tolerant of losing a copy. Missense variants: 331 observed, 453.99 expected, observed/expected ratio (o/e) 0.73, 90% interval 0.67 to 0.8. Synonymous variants: 170 observed, 165.47 expected, observed/expected ratio (o/e) 1.03, 90% interval 0.91 to 1.17.
Homologues: Orthologues: chimpanzee RRM2 (99% identical), macaque RRM2 (99% identical), dog RRM2 (97% identical), guinea pig RRM2 (94% identical), mouse Rrm2 (92% identical), rat Rrm2 (90% identical), tropical clawed frog rrm2 (84% identical), zebrafish RRM2 (83% identical), rabbit RRM2 (79% identical), Drosophila melanogaster RnrS (70% identical), Caenorhabditis elegans rnr-2 (60% identical). Paralogues in human: RRM2B (70% identical).
Diseases named in the same sentence as RRM2 in open-access papers:
RRM2 is named in the same sentence as 197 diseases in open-access papers, as found by Europe PMC text mining. Sharing a sentence is not in itself a finding about the gene and the disease. The quoted sentences say what the papers report.
breast cancer (103 papers, 2009 to 2026). A primary or metastatic malignant neoplasm involving the breast. "RRM2 is implicated in the progression of various cancers, including breast cancer, lung cancer, liver cancer, kidney cancer, glioma, and pancreatic cancer, among others." (PMID 39884577, 2025). "High expression of RRM2 has been associated with depressing survival outcomes in a variety of cancers, including breast cancer, gastric cancer, and bladder cancer." (PMID 41333212, 2025). "Our current study also reports that the CCND1 and RRM2 upregulation associated with palbociclib-resistant breast cancers decreases upon ribonucleotide reductase inhibition." (PMID 38473336, 2024). "The over-expression of RRM2 has been linked to higher proliferation and invasiveness of malignant cells, and the upregulation of RRM2 in breast cancer suggests it to be a possible prognostic indicator." (PMID 38741183, 2024). "For example, adenosine monophosphate deaminase 1 (AMPD1) and ribonucleotide reductase regulatory subunit M2 (RRM2), which are involved in purine metabolism, have been associated with survival in breast cancer patients." (PMID 38169859, 2023). "In recent years, RRM2 has been implicated in tumor progression in many cancers, including breast cancer, ovarian endometriosis, retinoblastoma, renal cell carcinoma, oral squamous cell carcinoma, and prostate cancer." (PMID 37699023, 2023). "Integrative metabolomics and gene expression revealed association of RRM2 expression with aggressive breast cancer and tamoxifen resistance, notably pharmacological or genetic inhibition of RRM2 sensitized tumours to tamoxifen treatment." (PMID 36997866, 2023). "RRM2 is associated with poor overall survival of breast cancer patients and can become a useful target for diagnosing and treating patients." (PMID 35409038, 2022). "Our study found that in 1,350 breast cancer patients, the expression of RRM2 was significantly associated with age, PAM50 classification, ER status, PR status, Her-2 status, menopause, or tumor grade (P<0.05)." (PMID 35290409, 2022). "Analysis of 159 breast cancer patients revealed that the RRM2 gene levels were significantly associated with poor OS and PFS." (PMID 36202136, 2022). "RRM2 can be used as a biomarker, and is associated with the survival and prognosis of breast cancer patients." (PMID 35290409, 2022). "The results showed that in stage 1 and stage 2 breast cancer patients, the high expression of RRM2 was associated with poor OS." (PMID 35290409, 2022). "Hub genes, namely TOP2A, MELK, PBK, NUSAP1, and RRM2, are closely associated with the occurrence and pathogenesis of breast cancer." (PMID 34094915, 2021). "This study shows that hub genes associated with breast cancer pathogenesis, namely RRM2, TOP2A, PBK, MELK, and NUSAP1, are gradually upregulated from NME to DCIS and then downregulated in IDC." (PMID 34094915, 2021). "Overexpression of RRM2 was shown to be associated with an unfavorable prognosis in HER-2 positive breast cancer patients." (PMID 33123291, 2020). "In Kaplan–Meier plotter survival analysis, the overexpression of RAC1 and RRM2 were shown to be associated with an unfavorable prognosis in HER-2 positive breast cancer patients." (PMID 31895772, 2020). "The present bioinformatics analysis showed that RRM2 was overexpressed in breast cancer patients to normal tissues and was associated with worse survival." (PMID 33123291, 2020). "Overexpression of RRM2 was strongly associated with worse survival in breast cancer and increased expression was shown in tamoxifen resistant patients." (PMID 33186389, 2020). "Compared with normal tissues, RRM2 is overexpressed in breast cancer patients and is associated with poor survival." (PMID 33123291, 2020). "High expression of RRM2 was associated significantly with decreased survival in all breast cancer subtypes and increased expression was shown in tamoxifen-resistant patients." (PMID 31777591, 2019).
breast cancer (continued). "In summary, the present bioinformatics analysis showed that RRM2 was overexpressed in breast cancer patients with respect to normal tissues and was associated with a worse survival." (PMID 30898978, 2019). "Overall, RRM2 was significantly related to aggressiveness and associated with poor outcome in breast cancers, especially in ER-negative breast cancer." (PMID 25213022, 2014). "The association of RRM2 protein levels with clinicopathological features of breast cancer was analyzed in the ZJU set." (PMID 25213022, 2014). "Multivariate Cox proportional hazard analysis confirmed that high levels of RRM2 protein were significantly and negatively associated with OS of breast cancer patients." (PMID 25213022, 2014). "As RRM2 mRNA levels increased, the outcome for the breast cancer patient became worse, and the relative risk of death increased in a dose-dependent manner." (PMID 25213022, 2014). "It was revealed that RRM2 mRNA levels were significantly associated with poor outcome in breast cancer patients." (PMID 25213022, 2014). "Besides being a therapeutic target, RRM2 also serves as a diagnostic and therapeutic biomarker in liver cancer and breast cancer." (PMID 40625451, 2024). "RRM2 is one of the important prognostic markers in cancer, it was found to be associated with large tumour size, positive lymph nodes and shorter survival in breast cancer." (PMID 34986845, 2022). "Furthermore, the high expression of RRM2 was associated with poor OS in breast cancer patients characterized by specific molecular subtypes (Luminal A subtype and Normal-like subtype) and specific stages (stage 1 and stage 2)." (PMID 35290409, 2022). "Finally, we defined pathways associated with the high expression of RRM2 and breast cancer progression through GSEA analysis." (PMID 35290409, 2022). "To determine whether the high expression of RRM2 was associated with the molecular subtypes of breast cancer, we conducted KM survival analysis." (PMID 35290409, 2022). "Finally, We performed Gene Set Enrichment Analysis (GSEA) and obtained the relevant pathways associated with high expression of RRM2 potentially influencing breast cancer progression." (PMID 35290409, 2022). "This is the first study that reports the association of RRM2 expression and breast cancer." (PMID 35290409, 2022). "In support of decreased HDAC11 within LNs leading to increased RRM2 and distant metastasis, functioning as a “release mechanism,” we found that RRM2 is highly associated with poor disease-free survival in breast cancer, including patients with LN involvement at diagnosis." (PMID 31519896, 2019). "It was reported that RRM2 was associated with resistance of breast cancer cells to chemotherapy and endocrine agents and that targeting RRM2 may be a novel strategy for cancer treatment." (PMID 30898978, 2019). "Rrm2 encodes a ribonucleotide reductase and was reported as an indicator of tamoxifen resistant in luminal patients as well as decreased survival in patients of all breast cancer subtypes." (PMID 28212608, 2017). "Moreover, it was reported that RRM2 was associated with chemoresistance of breast cancer cells to adriamycin; suppression of RRM2 synthesis could enhance the chemosensitivity to toxic insult." (PMID 30898978, 2019). "Thus, our data indicated that RRM2 might contribute to breast cancer progression and drug insensitivity associated with KIF11 expression." (PMID 30898978, 2019). "RRM2 has been confirmed to be overexpressed in hepatocellular carcinoma, breast cancer, Ewing sarcoma and atypical teratoid rhabdoid tumors which is related to tumor progression and poor prognosis, and can also be used as a key marker for aggressive tumors." (PMID 40510157, 2025). "While co-expression of CENPA and RRM2 have been previously analyzed in breast cancer, hepatocellular carcinoma, and in murine liver regeneration, their functional relationship has not been explored in PCa so far88–90." (PMID 41402347, 2025).
breast cancer (continued). "In breast cancer treatment, RRM2 is upregulated and contributes to resistance against GTI-2040, tamoxifen, Adriamycin, and cisplatin." (PMID 40697520, 2025). "RRM2 is aberrantly expressed in human tumors such as breast cancer, gastric cancer, adrenocortical cancer, pancreatic cancer and bladder cancer." (PMID 41333212, 2025). "Reduced expression of RRM2, cyclin D1, and NF-κB protein, and an elevated level of pH2AX result in decreased breast cancer growth and survival." (PMID 38473336, 2024). "Numerous studies suggest that RRM2 was dysregulated in various cancers, promoting the progression of cancers, such as renal cancer, liver cancer, lung cancer, breast cancer, colon cancer, ovarian cancer and bladder cancer 15-21." (PMID 38356717, 2024). "Ultimately, our data suggest a strategy to target RRM2, NF-κB and cyclin D1 to supplement traditional therapies as well as offering improved efficacy for breast cancer treatment." (PMID 38473336, 2024). "In previous studies, we have shown that RRM2 is upregulated in ER− as well as tamoxifen-resistant ER+ breast cancers." (PMID 38473336, 2024). "We also found evidence that RRM2 and cyclin D1 levels are upregulated in ER− palbociclib-resistant breast cancer, giving rise to a difficult-to-treat breast cancer population." (PMID 38473336, 2024). "We observed more than a 2.2-fold increase in CCND1 and 2.8-fold increase in RRM2 expression in PLB-resistant as compared to parental ER+ MCF7 breast cancer cells." (PMID 38473336, 2024). "To date, there are no studies examining the feasibility of a combination of CDK4/6 inhibitor palbociclib with an RRM2 inhibitor for treating both ER+ and ER− palbociclib-resistant breast cancers." (PMID 38473336, 2024). "Ultimately, our data suggest a strategy to target RRM2, NF-κB protein, and cyclin D1 to supplement traditional therapies while offering improved efficacy for breast cancer treatment." (PMID 38473336, 2024). "We also observed an upregulation of cyclin D1 and RRM2 protein levels in ER− palbociclib-resistant breast cancer cells, which suggests a possible mechanism for the development of palbociclib resistance." (PMID 38473336, 2024). "Multiple studies have reported a direct link between the overexpression of RRM2 in breast cancers and increased cell proliferation and invasiveness, as well as drug and chemotherapy resistance." (PMID 38473336, 2024). "We also found upregulation of cyclin D1, AKT and RRM2 with palbociclib resistance in MDA-MB-468 breast cancer cells compared to parental cells." (PMID 38473336, 2024). "Over-expression of RRM2 can promote breast cancer metastasis by activating PI3K/AKT signaling pathway to induce cell invasion, migration and vascular endothelial growth factor expression." (PMID 37056349, 2023). "have shown that promoters of the protein regulator of cytokinesis 1 (PRC1) and ribonuclease reductase 2 (RRM2) genes can be used in targeting breast cancer cells because these promoters exhibit strong gene expression similar to that driven by the CMV promoter." (PMID 38149057, 2023). "We determined association of XBP1-gene signature (RRM2, CDC6 and TOP2A) with the outcome in breast cancer." (PMID 36997866, 2023). "The level of RRM2 mRNA and protein expression in breast cancer tissues and cell lines was then analyzed using the BCIP database, qRT-PCR, western blotting." (PMID 35290409, 2022). "We also evaluated the impact of high-expression of RRM2 in different stages of breast cancer patients on OS." (PMID 35290409, 2022). "High expression of RRM2 had poor OS in patients with Luminal A subtype and Normal-like subtype breast cancer." (PMID 35290409, 2022). "Of note, DSCAM-AS1 promotes cell growth and impairs apoptosis of breast cancer cells via reducing miR-204-5p and enhancing RRM2 expression." (PMID 35692369, 2022). "In breast cancer, increased RRM2 protein level is strongly correlated with large tumour size, positive lymph node and relapse." (PMID 34986845, 2022).
breast cancer (continued). "We also detected the level of protein expression of RRM2 in breast cancer cell lines, and the same trend was obtained." (PMID 35290409, 2022). "To evaluate the effects of RRM2 expression on DMFS in breast cancer patients, we performed KM online survival analysis." (PMID 35290409, 2022). "To study the relationship between RRM2 expression and clinicopathological characteristics, we downloaded breast cancer patient data from the METABRIC database, which contained 2509 breast cancer samples." (PMID 35290409, 2022). "We only performed a few experiments to clarify the mRNA and protein expression levels of RRM2, therefore, the role and mechanism of RRM2 in breast cancer cells and breast cancer tissues need to be further verified and explored by our subsequent studies." (PMID 35290409, 2022). "RRM2 is also related to poor prognosis and overexpressed in a variety of human cancers, such as breast cancer, lung cancer, colorectal cancer, glioma, renal cell carcinoma, and prostate cancer." (PMID 35911380, 2022). "Using the BCIP database and real-time-PCR, and western blotting, RRM2 mRNA and protein expression of RRM2 in breast cancer tissues and cell lines were evaluated." (PMID 35290409, 2022). "Knocking down of RRM2 significantly decreased proliferation during S phase of cell cycle and induced tamoxifen resistance in breast cancer by regulating cell growth and DNA damage via the (AKT)-induced protein kinase B reversal." (PMID 34986845, 2022). "We then detected the relative mRNA expression of RRM2 in 45 breast cancers and their paired adjacent normal tissues by qRT-PCR." (PMID 35290409, 2022). "The protein expression of RRM2 was significantly increased in breast cancer tissues compared to adjacent normal tissues." (PMID 35290409, 2022). "Univariate and multivariate Cox regression analysis showed that RRM2 can be used as an independent prognostic factor, which is significantly related to OS in patients with breast cancer." (PMID 35290409, 2022). "The correlation between the expression level of RRM2 and the clinicopathological characteristics of breast cancer patients in the METABRIC database." (PMID 35290409, 2022). "Public databases were used to analyze the expression of RRM2 in breast cancer and its prognostic value." (PMID 35290409, 2022). "This study was performed by investigating RRM2 protein expression in breast cancer and correlating the results with other clinicopathological variables using immunohistochemistry and tissue microarrays." (PMID 34986845, 2022). "First, we confirmed that RRM2 is highly expressed in breast cancer tissues through multiple data sets (METABRIC, TCGA Agilent, TCGA RNA-seq, GSE5364)." (PMID 35290409, 2022). "Other studies found that silencing of RRM2 weakened breast cancer cell invasion and migration by controlling the PI3K signalling pathway." (PMID 34986845, 2022). "RRM2 expression was significantly correlated with age, tumor size, grade, menopausal status, molecular typing, ER, PR, and Her-2 of patients with breast cancer(P<0.05)." (PMID 35290409, 2022). "Next we verified that the expression of RRM2 in breast cancer cell lines is up-regulated by qRT-PCR and western blotting, which increases the reliability of the data." (PMID 35290409, 2022). "RRM2 regulates invasive and migrative abilities of breast cancer cells via the PI3K/AKT signaling pathway, thus inducing the metastatic potential of breast cancer." (PMID 35248107, 2022). "Other investigators have studied the prognostic significance of RRM2 in breast cancer cases, and it was found that increased RRM2 protein levels strongly correlated with large tumour size, positive lymph nodes and relapse." (PMID 34986845, 2022). "Our study analyzed the prognostic role of highly expressed RRM2 in various breast cancer subtypes, and finally we focused on the prognostic role of RRM2 in Luminal A breast cancer—an estrogen receptor-positive subtype of breast cancer." (PMID 35290409, 2022).